INS (insulin)
Diseases named in the same sentence as INS in open-access papers (continued):
Sharing a sentence is not in itself a finding about the gene and the disease.
Hyperinsulinemia (continued). "However in this study, hyperinsulinemia was applied under euglycemic conditions, a situation unlike that observed with GPR40 agonist treatment where increases in insulin are dependent on elevations in circulating glucose." (PMID 28542610, 2017). "However, abnormally high levels of insulin occur in only a subset of children with ONH, and previous authors have ruled out hyperinsulinemia as a growth factor in their respective studies of this patient population." (PMID 26937243, 2016). "On the other hand, BALB/c envenomed group did not present differences in insulin production compared to BALB/c control, although hyperinsulinemia has been reported previously during envenoming by the scorpion Mesobuthus tamulus concanesis and even by T. serrulatus." (PMID 27660634, 2016). "By decreasing the circulating levels of insulin and IGF-1, metformin may ameliorate this negative effect of hyperinsulinemia in diabetic patients." (PMID 25050322, 2014). "Insulin can relax vascular tones through the phosphatidylinositol 3 kinase (PI3K)/Akt-dependent nitric oxide (NO) production, and simple hyperinsulinemia may not necessarily induce hypertension." (PMID 24982885, 2014). "Parallel NOx and insulin increment and negative correlation of CRP and insulin in HC rabbits may be suggestive a protective role of hyperinsulinemia in early atherosclerosis." (PMID 23497719, 2012). "Hyperinsulinemia was seen as early as sevenweeks into the HCD diet in wild type littermates, but not in PKA Cβ null mice.An insulin sensitivity test showed that PKA Cβ null mice do not develop insulinresistance associated with the high caloric diet as wild type littermates do." (PMID 20448293, 2010). "Hyperinsulinemia disrupts the physiological balance between insulin and growth hormone: it can induce elevated IGF1 secretion (which subsequently suppresses GH to subnormal levels) and directly inhibit GH synthesis and release, leading to a negative correlation between insulin and GH levels." (PMID 41282298, 2025). "Hyperactivation of mTOR complex 1 (mTORC1) in response to repeated postprandial hyperinsulinemia may contribute to negative feedback inhibition of insulin receptor substrate (IRS) proteins, particularly IRS-1, impairing downstream insulin signaling via the PI3K-Akt pathway." (PMID 40806495, 2025). "The hypoglycemic action of SGLT2-I by excreting glucose in the urine may make a decisive difference in treating type 2 DM because, unlike insulin secretagogues and other hypoglycemic drugs that stimulate insulin secretion, SGLT2-I does not induce hyperinsulinemia." (PMID 38304078, 2024). "An in vivo study showed that insulin concentration (10−9–10−7 mol/L) induced VCAM-1 expression and markedly increased TNF-α via NF-kB activation and IkB-α accumulation, so we suspect that hyperinsulinemia stimulates the expression of VCAM-1, not the blood pressure." (PMID 37822716, 2023). "While we do not exclude that this peak in insulin earlier in the disease may still play a role, our study clearly demonstrates that the exercise pressor reflex can be exaggerated in T2DM without the concurrent presence of hyperinsulinemia." (PMID 36703927, 2022). "Unfortunately, we could not measure insulin tolerance or insulin sensitivity after Abn-CBD treatment, but the absence of hyperinsulinemia without increase in fasting glucose levels indirectly suggest that Abn-CBD might improve insulin sensitivity in our mouse model." (PMID 32210914, 2020). "Interestingly, despite the prevailing hyperinsulinemia, plasma c-peptide more than doubled in response to the OGL, after which it waned over time; this, however, had only a small (~10–15%) effect on plasma insulin levels and was not different between groups." (PMID 31474750, 2019).
Hyperinsulinemia (continued). "However, the effects of chronic hyperinsulinemia are unlikely to evoke in critical illness and data on the pathophysiological mechanism in ICU patients are scarce, although it is known that the regular insulin pathways react differently on exogenous insulin." (PMID 30742240, 2019). "Although hyperinsulinemia was previously reported in male C57BL6 ANXA1 KO mice on chow diet, in our study chow-fed female Balb/c ANXA1 KO mice only showed a non-significant trend towards elevated plasma insulin, a discrepancy likely attributable to strain- and sex-specific differences." (PMID 24312665, 2013). "Furthermore, the lungs of mice treated with insulin showed activation of β-catenin by PI3K/Akt, which is a positive regulator of epithelial-mesenchymal transition and fibrosis, suggesting that hyperinsulinemia may have negative impacts on airway structure and function." (PMID 38398039, 2024). "Moreover, although GDM women typically have elevated insulin as compared to normal pregnant women, which may stimulate fetal growth, infusion of sEVs isolated from GDM women in our pregnant mice did not replicate hyperinsulinemia." (PMID 36239315, 2022). "However, the fact that PCOS does not appear in every woman with IR or hyperinsulinemia and the fact that not every woman suffering from PCOS presents IR, suggests that there must be another malfunction that favors androgen excess in response to insulin or other triggering factors." (PMID 35457152, 2022). "Finally, similar to the exogenous action of insulin on androgen excess in women with T1D, we hypothesize that the use of insulin in women with GDM (with or without PCOS) might also aggravate hyperinsulinemia in pregnancy; however, this phenomenon and its potential complications await further study." (PMID 36733795, 2022). "Taken together, these data indicate that in the presence of insulin, the IR-A and to a lesser extent the IR-B isoform elicit several biological responses from TNBC cells, which may explain the negative prognostic effect of hyperinsulinemia in obese patients with BC." (PMID 34831367, 2021).
Glucose intolerance (2,491 papers, 2002 to 2026). Glucose intolerance (GI) can be defined as dysglycemia that comprises both prediabetes and diabetes. "Together, these results demonstrate that combined loss of CHD3 and CHD4 compromises β-cell survival and insulin secretory capacity, contributing to the glucose intolerance observed in Chd3/4Δβ mice." (PMID 41282155, 2025). "Mice engineered to carry the BAF60aV278M mutation exhibited glucose intolerance, reduced insulin secretion, and diminished expression of Nkx6.1-target genes, phenocopying BaβKO mice." (PMID 41052246, 2025). "While β-cell-specific loss of CHD3 alone had little effect, combined deletion of CHD3 and CHD4 caused severe glucose intolerance, impaired insulin secretion, and reduced β-cell area." (PMID 41282155, 2025). "Elevated acetyl-CoA levels persist regardless of feeding state and are associated with whole-body glucose intolerance, reduced insulin-stimulated glucose uptake in glycolytic muscle, and impaired glucose uptake during exercise." (PMID 39746949, 2025). "In vivo studies in rodents have suggested that A1-adenosine receptor activation in WAT improves glucose tolerance and insulin sensitivity, and its deficiency leads to glucose intolerance and impaired insulin action." (PMID 41048440, 2025). "In rodents, senescent cell accumulation causes glucose intolerance, whereas removing p16Ink4a-expressing cells restores glucose levels and insulin sensitivity." (PMID 41471323, 2025). "The OGTT and ITT also showed that exposure to BPA caused whole‐body glucose intolerance and impaired insulin sensitivity in F0 male mice." (PMID 39792613, 2025). "In animal models, eosinophil deficiency in AT causes weight gain, decreased insulin sensitivity, and glucose intolerance compared to wild-type animals." (PMID 41007770, 2025). "A 10-week trial of high-intensity atorvastatin therapy demonstrated increased insulin resistance and compensatory insulin secretion, suggesting a shift toward glucose intolerance in susceptible individuals." (PMID 40746725, 2025). "In this study, we found that paternally multi-generational HFD caused mild insulin insensitivity and glucose intolerance." (PMID 41220714, 2025). "GTT and ITT results revealed that Klf9 deficiency improved glucose intolerance and enhanced insulin sensitivity when the mice were maintained on a high‐fat diet." (PMID 40717541, 2025). "In vivo, genetic, or pharmacological disruption of the GLP-1R causes glucose intolerance in part due to impaired insulin secretion." (PMID 40526441, 2025). "Downregulation of Autophagy-Related Gene 7 (ATG7) in POMC neurones impairs autophagy in the hypothalamus, leading to decreased insulin sensitivity, accelerated glucose intolerance, and increased risk of developing T2DM." (PMID 41044789, 2025). "The multivariable analysis identified six significant factors associated with postpartum glucose intolerance, including the use of oral medication and insulin during pregnancy and physical inactivity." (PMID 41523956, 2025). "Urea, a distinct byproduct of arginase-mediated L-arginine metabolism, has been linked to β-cell malfunction, decreased insulin sensitivity, and glucose intolerance." (PMID 40810072, 2025). "Eosinophil-derived IL-4 and IL-13 promote M2 macrophage polarization and adipocyte maturation, enhancing lipid storage and insulin sensitivity, whereas eosinophil deficiency leads to impaired adipogenesis, ectopic lipid deposition, and glucose intolerance." (PMID 41010970, 2025). "Loss of hepatic ASPG dramatically alleviated glucose intolerance, potentiated insulin secretion in response to glucose feeding, and therefore manifested a low postprandial blood glucose level and a high insulin level." (PMID 40760121, 2025). "This disruption of estrogen signaling can lead to glucose intolerance, impaired insulin sensitivity, and increased risk of T2DM." (PMID 40508108, 2025).
Glucose intolerance (continued). "High FFA plasma levels are associated with glucose intolerance, disrupted muscle insulin signalling, increased hepatic gluconeogenesis, and reduced insulin response to glucose." (PMID 40216734, 2025). "Elevated tryptamine levels have been linked to glucose intolerance in patients with T2D, and acute IP administration impaired insulin sensitivity in mice." (PMID 39941095, 2025). "Zeeni’s study on 30 mice found that the CAF caused weight gain; increased energy intake, serum TC levels, insulin levels, and glucose intolerance; and caused heart, kidney, and liver damage compared to other diets." (PMID 40005380, 2025). "•Lesions of B7-H4 in β cells result in glucose intolerance due to a reduced β-cell mass and deficient insulin secretion." (PMID 39571901, 2024). "Glucose intolerance is often associated with perturbed glucose clearance, insulin resistance in peripheral tissues, and reduced insulin secretion by pancreatic beta-cells." (PMID 38393018, 2024). "The experimental group also exhibited glucose intolerance, impaired pancreatic beta-cell function, lower interleukin concentrations, and lower insulin levels, suggesting an association between fetal programming and metabolic alterations." (PMID 38397953, 2024). "Numerous studies have indicated that inadequate insulin secretion is the major cause of such glucose intolerance in fish." (PMID 39300527, 2024). "Failure to counter-regulate muscle insulin sensitivity by increasing Bmax capacity was associated with glucose intolerance and higher basal insulinemia." (PMID 38539988, 2024). "A consequence of low‐grade, chronic systemic inflammation is the underpinning of insulin resistance and pancreatic islet cell apoptosis, leading to insulin deficiency and therefore the progression of glucose intolerance (Fernández‐Real and Pickup 2012)." (PMID 39400977, 2024). "Knockout of islet and β-cell SENP1, in two separate Cre-driver models, led to IP glucose intolerance after 2-day HFD associated with a loss of insulin response." (PMID 38184650, 2024). "Aberrant pericyte-orchestrated islet inflammation was associated with impaired insulin production and secretion, loss of the β cell mature phenotype, and glucose intolerance." (PMID 38885342, 2024). "Diabetics’ glucose intolerance is caused by a diminished influence of incretins, since incretins provide 70% of the insulin response following meals." (PMID 38255264, 2024). "Lesion of B7-H4 in β cells results in glucose intolerance due to reduced β-cell mass and deficient insulin secretion, whereas overexpression of B7-H4 in β cells ameliorates glucose intolerance in HFD-fed mice." (PMID 39571901, 2024). "This restoration of the initial rise in insulin concentrations by Ki-16425 was associated with a dramatic correction of the glucose intolerance that was evident after glucose injection in RT-SAKO mice treated only with vehicle control." (PMID 38280449, 2024). "As expected, HFD feeding caused glucose intolerance and impaired insulin sensitivity in wild-type mice, as assessed by GTT and ITT." (PMID 39138413, 2024). "Specifically, knocking out B7-H4 in β cells results in glucose intolerance due to decreased β-cell mass and deficient insulin secretion, whereas overexpressing B7-H4 in β cells ameliorates glucose intolerance in HFD-fed mice." (PMID 39571901, 2024). "In young adulthood, Kcnk16 L114P causes glucose intolerance due to a reduction in glucose-stimulated insulin secretion mediated by enhanced β-cell Vm hyperpolarization and reduced glucose-stimulated Ca2+ entry." (PMID 38700926, 2024). "RyR2-mediated Ca2+ release contributes to glucose-mediated insulin secretion and pathogenic RyR2 mutations cause glucose intolerance in humans and mice." (PMID 38444585, 2024).
Glucose intolerance (continued). "A hepatokine, FETUB, which is regulated by steatosis and causes glucose intolerance by modulating insulin-independent glucose metabolism and is upregulated in T2D patients, was also significantly downregulated after chiglitazar treatment." (PMID 38182717, 2024). "In summary, this study confirmed that glucose intolerance in individuals with PI-CF was associated with delayed insulin secretion." (PMID 39093413, 2024). "Disruptions in SIRT1 activity are linked to T2DM and other metabolic dysfunctions; decreased SIRT1 expression and activity have been linked to poor insulin signaling and glucose intolerance." (PMID 38931292, 2024). "Consistently, β-cell-specific Bhlhe40 deficiency improves insulin secretion and glucose intolerance in ob/ob mice." (PMID 38673770, 2024). "In mice, Cav1.2 was the only LVGCC and the knockout of CACNA1C was lethal (glucose intolerance and loss of first-phase insulin secretion were observed)." (PMID 36901708, 2023). "We showed that in young‐adult mice clopidogrel treatment resulted in glucose intolerance caused by decreased glucose‐stimulated insulin secretion." (PMID 37490001, 2023). "Estradiol replacement in OVX mice reduced body weight, body fat, glycemia, and plasma insulin associated with reduced glucose intolerance." (PMID 37372993, 2023). "It is well known that glucose intolerance associated with high‐fat feeding leads to increased insulin and leptin, as well as decreased HMW‐adiponectin, in serum." (PMID 37845194, 2023). "METTL14 deficiency has been also demonstrated to decreased insulin secretion and lead to glucose intolerance." (PMID 36891946, 2023). "The action of reactive oxygen species with a simultaneous massive increase in cytosolic calcium concentration causes rapid destruction of the β-cells, which decreases insulin production causing glucose intolerance." (PMID 37760895, 2023). "When gap junction coupling and [Ca2+] synchronization are perturbed upon a genetic deletion of Cx36, first-phase insulin secretion and pulsatile second-phase secretion are diminished, causing glucose intolerance." (PMID 38018905, 2023). "Although PPGLs are well known to be associated with glucose intolerance, there are limited studies available that explore the effect on insulin secretion and sensitivity." (PMID 36982228, 2023). "It is also of note that Prevotellacoprishowed to be associated with an altered glucose metabolism leading to glucose intolerance and reduced insulin sensitivity due to the presence of the LeuBgene31." (PMID 37438382, 2023). "Our findings suggest that glucose intolerance in prepubertal or early pubertal children with T1D is accompanied by incomplete fatty acid oxidation while total daily insulin dose is associated with preferential catabolism of fats relative to amino acids." (PMID 37715520, 2023). "Knockout of D2 receptors in the insulinoma cell line INS-1 832/13 resulted in increased insulin secretion, but the global D2R knockout (KO) in mice impaired insulin secretion and caused glucose intolerance." (PMID 38002300, 2023). "Blockade of pancreatic D2R in mice causes glucose intolerance by decreasing insulin production and decreasing β-cells mass." (PMID 38002300, 2023). "The resulting impaired insulin secretion initiates the onset of glucose intolerance, which is a hallmark of CFRD." (PMID 37893045, 2023). "Platelet depletion in young‐adult mice leads to glucose intolerance caused by decreased glucose‐stimulated insulin secretion." (PMID 37490001, 2023). "Isolated fasting glucose intolerance is uncommon in TS and paradoxically, a reduction of fasting insulin and plasma glucose concentrations has been associated with a deterioration in glucose tolerance in TS." (PMID 36875465, 2023). "β-cell secretory capacity and age-related insulin insensitivity were identified as causes of glucose intolerance among young adults in a longitudinal cohort study." (PMID 37601212, 2023).